GHR (growth hormone receptor)
Diseases named in the same sentence as GHR in open-access papers (continued):
Sharing a sentence is not in itself a finding about the gene and the disease.
dwarfism (continued). "In chickens, several kinds of GHR mutations would result in dwarfism and reduced growth." (PMID 31208008, 2019). "Dwarfism in an individual may be caused by more than one kind of GHR mutation and may result from defects in others genes." (PMID 29748515, 2018). "However, the dose individually affects the GHR mutations causing dwarfism." (PMID 29748515, 2018). "Since Laron’s first description of dwarfism in humans due to defects in the GHR, an enormous amount of progress has been made to understand how GH and IGF-1, as well as their binding proteins, receptors, and signaling pathways, contribute to linear growth." (PMID 38241182, 2024). "Defective GHR signaling, as seen in human Laron dwarfism, resulted in low plasma IGF-1 concentrations and limited growth, but also marked absence in the development of breast cancer and type 2 diabetes." (PMID 39459020, 2024). "An animal model mimicking Laron syndrome (hereditary dwarfism resulting from defects in the GHR gene in humans) was developed by disrupting the mouse Ghr/binding protein (Bp) gene." (PMID 36452322, 2022). "As a result of the GHR mutation there is a drastic reduction in IGF1 biosynthesis in the liver and, probably, other extrahepatic tissues, with ensuing dwarfism." (PMID 35283485, 2022). "LS is caused by the mutation or deletion of the GHR gene, or post-receptor pathways, leading to congenital IGF1 deficiency and dwarfism." (PMID 34204736, 2021). "For instance, the G62V mutation in exon 4, a heterozygous mutation (V144I) within exon 6 of the GHR, a dinucleotide deletion on exon 7 of the GHR gene, and even a GT-repeat microsatellite in the GHR 5’UTR can result in dwarfism." (PMID 29748515, 2018). "Sexual maturation in male and female GHR-/- mice is delayed by approximately 1 week, and humans with Laron dwarfism were reported to exhibit a similar reproductive phenotype." (PMID 30542372, 2018). "Because aberrant GHR elicits the dwarfism phenotype, it is important in the functional mechanism that how GHR acts on skeletal muscle in SLD in response to let-7b." (PMID 24082823, 2013). "With regard to sex-linked dwarfism, which is caused by mutations in the GHR gene located on chromosome Z, no significant SNPs in or around this gene were detected." (PMID 36980905, 2023). "However, the precise molecular mechanism of how the GHR gene mutations caused so many phenotypic and physiological alterations still remains unclear, and the core regulatory pathways and gene interactional networks underlying dwarfism also need to be further explored." (PMID 26927061, 2016). "Based upon our previous study, miRNA regulation, which implicates GHR as well, may be important in dwarfism formation." (PMID 24082823, 2013). "Growth hormone receptor (GHR) knockout mice have an extended lifespan, but the trade‐off is dwarfism." (PMID 36619246, 2020). "The long-lived GH-resistant GH receptor (GHR)-KO mice which have high GH level, as well as Ames dwarf and Snell dwarf mice lacking GHexhibit dwarfism, increased subcutaneous adiposity, change in tissue sizes, and increased insulin sensitivity." (PMID 25239873, 2014). "However, expression of GHR in dwarf chickens was significantly higher than that in normal chickens, and very little IGF-1 gene expression was observed in dwarf chickens, further illustrating that the GH-independent dwarfism is due to dysfunctional GHR protein in accordance with a mutant GHR gene." (PMID 24082823, 2013).
Insulin resistance (36 papers, 2011 to 2025). Increased resistance towards insulin, that is, diminished effectiveness of insulin in reducing blood glucose levels. "We found that a higher baseline GHR level and a greater increase in GHR level between baseline and 36 months were positively associated with hyperglycemia, insulin resistance, and lower measures of beta cell function in youths with T2D." (PMID 38421647, 2024). "Additional research was warranted to investigate potential correlations between GHR and other metabolic conditions, such as hypertension, insulin resistance, and cardiovascular risk." (PMID 39296907, 2024). "The aim of this study was to identify the new role of GHR in systemic insulin resistance and explore the underlying mechanism." (PMID 34373742, 2021). "Accordingly, 12-month-old transgenic mice that overexpress a GHR antagonist exhibited improved insulin sensitivity and learning, whereas overexpressed GH caused insulin resistance and impaired memory retention." (PMID 31939479, 2019). "For instance, GHR knockout mice have reduced levels of pro-inflammatory cytokines implicated in development of insulin resistance (TNF-α and IL-6), possibly as a consequence of anti-inflammatory effects of increased levels of adiponectin in these mutants." (PMID 23483710, 2013). "We have previously shown that loss of GHR signaling in the skeletal muscle in the mGHRKO mice is associated with a marked protection from the development of HFD-induced insulin resistance, as assessed by several parameters." (PMID 23024761, 2012). "There is evidence that high levels of GHR can accelerate systemic insulin resistance, which may partly explain the observed associations." (PMID 38623619, 2024). "And, the altered gut microbiota in turn affects the bacterial metabolites that may contribute to the insulin resistance and liver lipid accumulation caused by liver GHR disruption." (PMID 37306416, 2023). "In mice, early muscle-specific deletion of Growth Hormone Receptor (GHR) causes several symptoms including insulin resistance, while adult muscle-specific GHR deletion causes entirely different effects, including increased metabolic rate and insulin sensitivity on a high-fat diet." (PMID 31944178, 2020). "Insulin resistance and increased triglycerides are also present in male aHepGHRkd mice, while systemic metabolic endpoints are only modestly modified in females, indicating that females are relatively protected from steatosis and liver injury that result from the loss of hepatic GHR." (PMID 38370444, 2024). "However, whether hepatic GHR overexpression or activation is a cause of insulin resistance is still unknown." (PMID 34373742, 2021). "However, it is currently unclear whether hepatic GHR overexpression or activation is a cause of insulin resistance in commonly used mouse models of T2DM." (PMID 34373742, 2021). "The “paradoxical” cognitive improvement and protection against hypothalamic inflammation in aged GHR-knockout mice may be related to the higher insulin sensitivity observed in these animals as insulin resistance has been linked with impaired cognition and is a risk factor for Alzheimer’s disease." (PMID 31939479, 2019). "SOCS2 mitigates the adverse effects of proinflammatory cytokines and down-regulates GHR signaling, which can exacerbate insulin resistance by promoting hepatic glucose production." (PMID 40362828, 2025). "Our results together with previous studies have proved that both the congenital and adult-onset liver GHR disruption result in insulin resistance and hepatic steatosis." (PMID 37306416, 2023). "Knocking out the GHR specifically in the liver throughout the lifespan led to insulin resistance and glucose intolerance in both sexes, and liver steatosis in males." (PMID 37881503, 2023). "Together, this evidence provides important insights into systemic insulin resistance mediated by hepatic GHR." (PMID 34373742, 2021).
Insulin resistance (continued). "Since this phenotype is not observed in the mice with ablated GHR in the AgRP/NPY, POMC and VMH neurons, it is likely that other LepR-expressing cells mediate the insulin resistance of the mice with diminished GHR signaling in the LepR cells." (PMID 31939479, 2019). "Mavalli and colleagues report that muscle specific disruption of GHR in male mice produces increased adiposity with insulin resistance, and glucose intolerance." (PMID 26233957, 2015). "This evidence suggests that insulin resistance in CUG-SGA rats is associated with impairment of IRS-1-PI3K-AKT signaling, which results from GHR signaling-induced upregulation of SOCS3 expression." (PMID 24963636, 2014). "We have shown previously that liver-specific deletion of GHR result in lipid accumulation in hepatocytes and insulin resistance." (PMID 25566190, 2014). "Biologically, this could indicate that GHR levels up to this point significantly reflect metabolic disturbances, such as insulin resistance, dyslipidemia, or impaired glucose metabolism, which are key contributors to gallstone formation." (PMID 39950129, 2025). "Collectively, our above results suggested that hepatic GHR overexpression facilitated insulin resistance in skeletal muscle and white adipose tissue, which might be relevant to impaired systemic insulin signaling." (PMID 34373742, 2021). "In addition, the serum insulin level and homeostatic model assessment of insulin resistance (HOMA-IR) index were significantly lower in GHR KO pigs." (PMID 34803486, 2021). "Thus, hepatic GHR overexpression induced systemic insulin resistance through intertissue crosstalk mediated by circulating RBP4." (PMID 34373742, 2021). "In our experiment, systemic insulin resistance was observed in the liver, skeletal muscle and white adipose tissue, which might be induced by hepatic GHR overexpression; hence, we presume that hepatokines could be responsible for this effect." (PMID 34373742, 2021). "Moreover, in contrast to global GHRKOs, mice with GHR deletion in muscles (MuGHRKO) are characterized by insulin resistance and glucose intolerance." (PMID 25855408, 2015). "Moreover, insulin resistance may directly blunt GH-induced intracellular signaling, as insulin has been shown to downregulate GH receptor (GHR) expression and impair JAK2/STAT5 activation—key pathways for GH-mediated growth promotion." (PMID 41282298, 2025). "Therefore, it is possible that an increase in GHR level due to increased BMI and insulin resistance in individuals with T2D may attenuate GH activity in the liver to stimulate IGF-1 synthesis." (PMID 38421647, 2024). "Consequently, hepatic GHR overexpression induces systemic insulin resistance." (PMID 34373742, 2021). "However, unlike mice with the congenital loss of hepatocyte GHR signaling, aHepGHRkd mice only develop mild insulin resistance, associated with an increase in insulin levels, without alterations in glucose tolerance, WAT lipolysis, or hepatic VLDL-TG release." (PMID 34685512, 2021). "Furthermore, since the liver functions as an endocrine organ in systemic insulin sensitivity, whether hepatic GHR is can affect hepatokine-regulated interorgan communication, thereby being involved in the pathogenesis of insulin resistance is unknown." (PMID 34373742, 2021). "Consistent with the negative association between GH and steatosis, mouse models with the congenital, liver-specific knockout of the GHR or its downstream effectors (JAK2 or STAT5) as adults exhibit steatosis, glucose intolerance, insulin resistance, and WAT lipolysis." (PMID 34685512, 2021). "We aim to confirm whether inhibiting GHR under baseline conditions can alter the post-receptor activity of GH and insulin signaling, and explore the possible mechanisms linking CUG and insulin resistance in SGA." (PMID 24963636, 2014).
Insulin resistance (continued). "The present data proved that GHR not only promoted the secretion of RBP4 from the liver by activating STAT5 but also maintained circulating RBP4 homeostasis and repressed renal clearance of RBP4 by provoking activation of the HIF1α/TTR axis, thus inducing systemic insulin resistance." (PMID 34373742, 2021).
breast carcinoma (35 papers, 2013 to 2024). "Our data showed that GHR deficiency significantly inhibited breast cancer cell lines and tumor growth, and induced cell apoptosis increase." (PMID 32069380, 2020). "Dysregulated PRL/PRLR or GH/GHR activity has been associated with the development of various cancers, including breast cancer." (PMID 33362552, 2020). "Breast cancer cells were accumulated in the G1 phase of the cell cycle and then suddenly decreased in S phase caused by GHR inhibition, indicating GHR deficiency prevented G1‐to‐S phase progression." (PMID 32069380, 2020). "Here, we attempted to find one mechanism underlying the influence of GHR on breast cancer progression." (PMID 32069380, 2020). "Recently, GHR is reported to be associated with cancer development and progression, including breast cancer and hepatocellular carcinoma." (PMID 32970612, 2020). "Recently, GHR has been reported to be associated with breast cancer development, but the molecular mechanism of GHR in this malignancy is not fully understood." (PMID 32069380, 2020). "IHC analysis of 72-breast cancer samples also revealed increased GHR expression was usually associated with lower ER expression." (PMID 30617282, 2019). "Immunohistochemical staining data indicated that primary breast cancers expressing high levels of GHR also stained strongly for pAKT, pmTOR, and ABCG2, demonstrating the association of GHR with these proteins in primary breast cancers." (PMID 30617282, 2019). "In this study, we provided the novel evidence that host EphA4 deficiency inhibited murine breast cancer growth and metastasis by reducing the EphA4‐GH receptor (GHR)‐IGF1 and/or EphA4‐IGF1 activities, which lead to decreasing IGF1 production." (PMID 26923183, 2016). "To verify whether GHR is associated with breast cancer progression by modulating the BRAF/MEK/ERK signaling pathway, we evaluated the roles of GHR silencing in the expression of p‐BRAF, p‐MEK and p‐ERK." (PMID 32069380, 2020). "Overall, these findings demonstrate that targeting GHR could be a novel therapeutic approach to overcome chemoresistance and associated metastasis in aggressive ER-ve breast cancers." (PMID 30617282, 2019). "In addition, we also observed that GHR expression was positively associated with ER−ve breast cancers, and the patients with these tumors exhibited poor survival." (PMID 30617282, 2019). "In breast cancer, as in GBMs, GHR expression is quite heterogeneous and 12% of cases overexpress GHR (239 out of 1980, mRNA z‐score 1.354, 55)." (PMID 35808822, 2022). "This preclinical study demonstrates the application of dual GHR/PRLR antibodies as a useful strategy for the treatment of breast cancer by impeding the PRLR signaling axis." (PMID 36714582, 2022). "To investigate the role of GHR in breast cancer cell apoptosis, we further performed apoptosis assay by PI and Annexin V staining." (PMID 32069380, 2020). "Studies have indicated that PRLR and GHR are closely related to the occurrence and development of breast cancer, and breast cancer cell endogenously express GHR, PRLR." (PMID 33362552, 2020). "On the basis of the results presented earlier, we conclude that GHR mediates breast cancer cell progression and apoptosis through controlling cell cycle in G1–S phase transition as a regulator of the BRAF/MEK/ERK signaling pathway." (PMID 32069380, 2020). "In this case, it is necessary to develop the dual-function GHR/PRLR antagonists with anti-breast cancer potential." (PMID 33362552, 2020). "Here, we stably inhibited growth hormone receptor (GHR) in breast cancer cell lines, which reduced cell proliferation, tumor growth and induction of apoptosis, and arrested the cell cycle at the G1–S phase transition." (PMID 32069380, 2020). "To investigate this issue, we stably inhibited GHR in breast cancer cell lines, which were observed to reduce cell proliferation, tumor growth and induction of apoptosis, and arrest the cell‐cycle arrest at the G1–S phase transition." (PMID 32069380, 2020).
breast carcinoma (continued). "Prolactin receptor (PRLR) and growth hormone receptor (GHR) are closely related to the occurrence and development of breast cancer, and breast cancer cell endogenously express GHR, PRLR and GHR-PRLR heterodimer." (PMID 33362552, 2020). "GHR inhibition, using the GHR antagonist, Pegvisomant, alone has been found to attenuate the growth of both colon and breast cancers." (PMID 33291663, 2020). "Studies have shown that the occurrence and development of breast cancer are closely related to GH/PRL, and PRLR and GHR are co-expressed on breast cancer." (PMID 33362552, 2020). "Western blotting assay showed that GHR protein levels were increased in breast cancer cells relative to normal cells (NMuMG and MCF10A)." (PMID 32069380, 2020). "Our results showed that GHR reduction led to the inhibition of breast cancer cell lines proliferation and tumor growth, the induction of cell apoptosis and the cell‐cycle arrest in G1–S phase transition." (PMID 32069380, 2020). "In prior studies, GHR has been verified to be a oncogene in some cancers, such as breast cancer, pancreatic ductal carcinoma and melanoma, but the role in THCA prognosis is firstly reported." (PMID 32849296, 2020). "GHR was stably knocked down in ER-ve breast cancer cells and its effect on cell proliferation, metastatic behavior, and chemosensitivity to docetaxel (DT) was assessed." (PMID 30617282, 2019). "GHR inhibition with pegvisomant (a GHR antagonist) induced apoptosis in breast cancer cells, which is consistent with our current findings." (PMID 30617282, 2019). "GHR expression was found increased in breast cancer cell lines compared to normal epithelial cell lines." (PMID 30617282, 2019). "The overexpression of GHR observed in primary breast cancer tissues and aggressive mouse mammary tumors suggest the involvement of GHR in breast cancer." (PMID 30617282, 2019). "GHR silencing drastically reduced the chemoresistant and metastatic behavior of ER-ve breast cancer cells and also inhibited AKT/mTOR pathway." (PMID 30617282, 2019). "We performed this study mainly to address the in vivo role of GHR in ER−ve breast cancer progression and chemoresistance." (PMID 30617282, 2019). "This study provides the first insight into the mechanism by which GH/GHR favors the metastasis of ER−ve breast cancer." (PMID 30617282, 2019). "Rajkumar Lakshmanaswamy and colleagues at Texas Tech University, El Paso, USA, investigated the role of growth hormone receptor (GHR) protein in human breast cancer cells." (PMID 30617282, 2019). "Our data illustrates that GHR knockdown largely enhanced the sensitivity of ER−ve breast cancer cells to DT." (PMID 30617282, 2019). "In summary, we show that GHR is overexpressed in ER−ve breast cancer cells and inhibiting GHR signaling reduces the activity of the JAK/STAT and AKT/mTOR pathways and inhibits EMT, growth, and metastatic behavior of ER−ve breast cancers." (PMID 30617282, 2019). "The data clearly suggested that GHR or ABCG2 knockdown sensitized the primary human breast cancer cells to DT." (PMID 30617282, 2019). "GHR knockdown in primary human breast cancer cells reduced their viability by ~50%, and DT treatment only inhibited the viability by 22%." (PMID 30617282, 2019). "This is the first study to demonstrate that GHR promotes the chemoresistance of ER−ve breast cancers by regulating ABCG2 levels." (PMID 30617282, 2019). "Statistical analysis of IHC data of 72 human breast cancer samples revealed a high correlation between GHR (40%), pAKT (73%), and pmTOR (75%) with ABCG2." (PMID 30617282, 2019). "Further analysis indicated that this treatment also induced apoptosis in the patient-derived breast cancer cells, indicating that the effects of GHR knockdown can be translated to clinical samples." (PMID 30617282, 2019).